BRAT1 (BRCA1 associated ATM activator 1)
Description:
Component of a multiprotein complex required for the assembly of the RNA endonuclease module of the integrator complex. Associates with INTS9 and INTS11 in the cytoplasm and blocks the active site of INTS11 to inhibit the endonuclease activity of INTS11 before formation of the full integrator complex. Following dissociation of WDR73 of the complex, BRAT1 facilitates the nuclear import of the INTS9-INTS11 heterodimer. In the nucleus, INTS4 is integrated to the INTS9-INTS11 heterodimer and BRAT1 is released from the mature RNA endonuclease module by inositol hexakisphosphate (InsP6). BRAT1 is also involved in DNA damage response; activates kinases ATM, SMC1A and PRKDC by modulating their phosphorylation status following ionizing radiation (IR) stress. Plays a role in regulating mitochondrial function and cell proliferation. Required for protein stability of MTOR and MTOR-related proteins, and cell cycle progress by growth factors.
Synonyms: BAAT1; C7orf27; MGC22916; NEDCAS; RMFSL
Tractability: PROTAC: UniProt records ubiquitination sites on it; ubiquitination databases record sites on it; its protein half-life has been measured.
Gene: Protein-coding gene on chromosome 7 (2,537,810 to 2,555,782, reverse strand). Ensembl gene ENSG00000106009.
Subcellular location: Nucleus; Cytoplasm
Subcellular location (Human Protein Atlas): Nucleoplasm
Gene Ontology:
Molecular function: protein binding; ribonuclease inhibitor activity
Biological process: apoptotic process; cell migration; cell population proliferation; DNA damage response; glucose metabolic process; integrator complex assembly; mitochondrion localization; positive regulation of cell growth; positive regulation of protein phosphorylation; protein localization to nucleus; response to ionizing radiation
Cellular component: cytoplasm; cytosol; membrane; nucleoplasm; nucleus
Genetic constraint (gnomAD): Loss-of-function variants: 75 observed, 65.37 expected, observed/expected ratio (o/e) 1.15, 90% interval 0.95 to 1.39. The synonymous counts are far from expectation, so gnomAD's model fits this gene poorly and the ratio says little. Missense variants: 1,203 observed, 1,029.6 expected, observed/expected ratio (o/e) 1.17, 90% interval 1.11 to 1.23. Synonymous variants: 615 observed, 488.62 expected, observed/expected ratio (o/e) 1.26, 90% interval 1.18 to 1.35.
Gene-disease validity (ClinGen):
ClinGen rates the evidence that BRAT1 causes each of these diseases.
neonatal-onset encephalopathy with rigidity and seizures (autosomal recessive): Definitive. A rare genetic neurological disorder characterized by neonatal onset of rigidity and intractable seizures, with episodic jerking already beginning in utero.
neurodevelopmental disorder with cerebellar atrophy and with or without seizures (autosomal recessive): Definitive. An an autosomal recessive disorder characterized by intellectual disability associated with ataxia, in which the cause of the disease is a variation in the BRAT1 gene.
Homologues: Orthologues: chimpanzee BRAT1 (99% identical), macaque BRAT1 (95% identical), dog BRAT1 (77% identical), guinea pig BRAT1 (75% identical), pig BRAT1 (75% identical), rat Brat1 (74% identical), mouse Brat1 (74% identical), tropical clawed frog brat1 (42% identical), zebrafish brat1 (34% identical), Drosophila melanogaster CG7044 (18% identical).
Diseases named in the same sentence as BRAT1 in open-access papers:
BRAT1 is named in the same sentence as 39 diseases in open-access papers, as found by Europe PMC text mining. Sharing a sentence is not in itself a finding about the gene and the disease. The quoted sentences say what the papers report.
microcephaly (6 papers, 2016 to 2026). A congenital or acquired developmental disorder in which the circumference of the head is smaller than normal for the person's age and sex. "Recessive mutations in BRAT1 cause lethal neonatal rigidity and multifocal seizure syndrome (RMFSL), a phenotype characterized by neonatal microcephaly, hypertonia, and refractory epilepsy with premature death." (PMID 35360849, 2022).
Ataxia (3 papers, 2022 to 2024). Ataxia refers to impaired coordination of voluntary muscle movement. "Recently, we identified a missense homozygous mutation in BRAT1 (p.V62E) that is associated with cerebellar atrophy, ataxia, ocular motor apraxia, and mild cognitive impairment, somewhat similar to that observed in DNA repair-defective diseases." (PMID 36028512, 2022). "Here, we reported a 10-year-old girl with severe intellectual disability, rigidity, ataxia or dyspraxia, and cerebellar atrophy on brain MRI; two BRAT1 variants in the trans configuration [c.1014A > C (p.Pro338 = ); c.706delC (p.Leu236Cysfs*5)] were detected using whole-exome sequencing." (PMID 35360849, 2022). "These patients present clinically with cerebellar atrophy, ataxia, ocular motor apraxia and mild cognitive impairment; a phenotype much milder in comparison to another known BRAT1 related disorders." (PMID 36028512, 2022). "Thus, based on the pathology of the BRAT1 patients in this study, we further link the improper processing of Integrator RNA substrates to cerebellar atrophy and ataxia." (PMID 36028512, 2022). "Moreover, we show that patient cells from BRAT1 related cerebellar ataxia exhibit increased levels of unprocessed UsnRNAs and alter gene expression and RNA processing." (PMID 36028512, 2022).
Cerebellar atrophy (3 papers, 2022). Cerebellar atrophy is defined as a cerebellum with initially normal structures, in a posterior fossa with normal size, which displays enlarged fissures (interfolial spaces) in comparison to the foliae secondary to loss of tissue. "Pathogenic variants in BRAT1 are associated with a spectrum of clinical syndromes ranging from Lethal Neonatal Rigidity and Multifocal Seizure syndrome (RMFSL) to Neurodevelopmental Disorder with Cerebellar Atrophy and with or without Seizures (NEDCAS)." (PMID 35620305, 2022).
epilepsy (3 papers, 2012 to 2023). A brain disorder characterized by episodes of abnormally increased neuronal discharge resulting in transient episodes of sensory or motor neurological dysfunction, or psychic dysfunction. "Similar to BRAT1, mutations in the human Integrator complex are associated with a severe recessive human neurodevelopmental syndrome, which is characterized by profound intellectual disability, epilepsy and subtle structural brain abnormalities." (PMID 36028512, 2022). "The destabilization of BRAT1 observed might underlie the catastrophic epilepsy and corticobasal neuronal degeneration observed in affected infants." (PMID 22279524, 2012). "More recently, biallelic BRAT1 mutations have been associated with a milder phenotype in patients with migrating focal seizures in the absence of rigidity or with nonprogressive congenital ataxia with or without epilepsy (NEDCAS)." (PMID 37009381, 2023). "Functional studies of BRAT1 and SNIP1 will expand our understanding of epilepsy and also deepen our knowledge of DNA damage repair and transcriptional regulation in cortical development and neuronal survival." (PMID 22279524, 2012).
Epileptic encephalopathy (3 papers, 2016 to 2022). A condition in which epileptiform abnormalities are believed to contribute to the progressive disturbance in cerebral function. "This case expands the spectrum of disease associated with BRAT1 variants and highlights the utility of genetic testing to identify the cause of developmental and epileptic encephalopathies where clinical heterogeneity within a spectrum of disease exists." (PMID 35620305, 2022). "Depending on the laboratory, BRAT1 may not be one of the genes sequenced as part of an epileptic encephalopathy panel." (PMID 27956813, 2016).
developmental delay (2 papers, 2018 to 2022). "KARs dysregulation may be at the basis of the drug-resistant seizures and developmental delay described in subjects with genetic mutations linked to other DNA repair proteins as in Breast Cancer 1-associated Ataxia Telangiectasia mutated activation-1 protein (BRAT1) gene." (PMID 35842432, 2022).
anemia (1 paper, 2019). A reduction in the number of red blood cells, the amount of hemoglobin, and/or the volume of packed red blood cells. "Notably, proteins decreased only after both combination treatments include proteins involved in the DNA damage response (DDR) like BRAT1, Fanconi Anemia Complementation Group I (FANCI) and CHEK1, indicating that the cells might be more prone to DNA damage." (PMID 30871073, 2019).
colorectal cancer (1 paper, 2022). A primary or metastatic malignant neoplasm that affects the colon or rectum. "Significant increases (> 0.6) in the AUC for BRAT1-Ab vs. esophageal squamous cell carcinoma (ESCC), gastric cancer, and colorectal cancer suggested that BRAT1-Ab exhibited better predictive potential for GI cancers than WDR1-Ab." (PMID 35656505, 2022).
glioma (1 paper, 2025). A benign or malignant brain and spinal cord tumor that arises from glial cells (astrocytes, oligodendrocytes, ependymal cells). "By a stable depletion of BRAT1 in GBM and glioma stem-like (GSC) cell lines, we observed a delay in DNA double-strand break repair and increased sensitivity to radiation treatment, corroborated by in vitro and in vivo studies demonstrating impaired tumor growth and invasion." (PMID 39833546, 2025).
lymph node metastasis (1 paper, 2022). "A multivariate survival analysis only disclosed statistically significant correlations between the serum BRAT1-Ab levels and lymph node metastasis (P = 0.05), CRP level (P = 0.05), and tumor depth (P = 0.03)." (PMID 35656505, 2022).
osteosarcoma (1 paper, 2014). A usually aggressive malignant bone-forming mesenchymal neoplasm, predominantly affecting adolescents and young adults. "When BRAT1 was knocked down in mouse embryonic fibroblasts (MEFs) and human osteosarcoma cell (U2OS), a constitutive level of apoptosis was increased." (PMID 25070371, 2014).
prostate carcinoma (1 paper, 2023). A carcinoma that arises from epithelial cells of the prostate gland. "Meanwhile, our previous findings suggest that BRAT1 may also be a potential protein for curcusone C to exert anti-prostate cancer activity, but this idea needs further proof." (PMID 37814239, 2023).
transient ischemic attack (1 paper, 2022). A brief attack (from a few minutes to an hour) of cerebral dysfunction of vascular origin, with no persistent neurological deficit. "Using serological antigen identification by cDNA expression cloning (SEREX) and western blot, we screened and detected the antigens BRCA1-Associated ATM Activator 1 (BRAT1) and WD Repeat Domain 1 (WDR1) in the sera of patients with transient ischemic attacks (TIA)." (PMID 35656505, 2022).
cancer (5 papers, 2014 to 2025). A tumor composed of atypical neoplastic, often pleomorphic cells that invade other tissues. "Firstly, the global total proteome of BRAT1-depleted cells indicates changes in proteins associated with cancer cell migration and invasion in line with the findings from our previous experiments." (PMID 39833546, 2025). "By taking advantage of BRAT1 knockdown cancer cell lines, we found that loss of BRAT1 expression significantly decreases cell proliferation and tumorigenecity both in vitro and in vivo." (PMID 25070371, 2014). "Notably, Cav-1, which was increased in our NCH644 BRAT1 KD proteomic dataset, has been implicated in modulating migration in a context-dependent manner in different cancer types." (PMID 39833546, 2025). "Therefore, down-regulation of tetraspanin and BRAT1, caused by EgKI-1, can contribute to cancer cell growth inhibition but additional study is required to identify the precise molecules and mechanisms of action of EgKI-1 in cancer cell growth inhibition." (PMID 30169534, 2018). "Here we show that BRAT1 plays a pivotal role in regulating cancer cell behaviour by impacting both migration and invasion, while also exerting an influence on the DDR." (PMID 39833546, 2025). "In vitro and in vivo cell proliferation and tumorigenicity were significantly reduced in BRAT1 KO cancer cell lines." (PMID 35656505, 2022). "In BRAT1 knockout (KO) cancer cell lines, the ROS levels were increased and mitochondrial membrane potential and ATP production decreased." (PMID 35656505, 2022). "The BRAT1 protein participates in DNA damage responses, cell growth, and apoptosis by interacting with the tumor-suppressor protein BRCA1 (breast cancer 1) and the ATM protein (ataxia telangiectasia mutated) in humans." (PMID 30093865, 2018). "Using RNA interference against human BRAT1, we generated stable BRAT1 knockdown cancer cell lines of U2OS, Hela, and MDA-MA-231." (PMID 25070371, 2014). "Finally, RASSF2 was amongst the most decreased proteins, implying the importance of BRAT1 potentially influencing cancer cell invasion." (PMID 39833546, 2025). "The total global proteome of NCH644 upon BRAT1 depletion (7273 proteins) suggested that 10% of proteins, which were downregulated (total 179 decreased proteins) are involved in movement, therefore potentially influencing cancer cell migration and invasion." (PMID 39833546, 2025). "Subsequent exploration of a cancer database showed that BRAT1 was upregulated in GI cancers." (PMID 35656505, 2022). "In current study, we found that BRAT1 is involved in cellular growth properties including cell proliferation and tumor growth, and required for mitochondrial homeostasis, describing new roles of BRAT1 in cell growth and metabolism, and providing novel strategies for cancer treatment." (PMID 25070371, 2014). "Therefore, BRAT1 plays key roles in cancer cell mitochondrial function." (PMID 35656505, 2022). "Moreover, BRAT1 protein is oncogenic in several different cancers." (PMID 35656505, 2022). "Curcusone D (CurD) leads to an impaired DDR, reduced cancer cell migration, and potentiated activity of the DNA damaging drug etoposide, in HeLa, MCF-7 and MDA-MB-231 cells, indicating a potential role of BRAT1 in therapy responses and tumor growth." (PMID 39833546, 2025). "However, BRAT1 may play vital roles in AS and cancer by influencing mitochondrial function." (PMID 35656505, 2022).
neurodevelopmental disorder (5 papers, 2022 to 2026). A behavioral and cognitive disorder with onset during the developmental period that involves impaired or aberrant development of intellectual, motor, or social functions. "Mutations in BRAT1 have been linked to severe neurodevelopmental disorders, highlighting the importance of these pathways for brain development and genome integrity." (PMID 41226651, 2025). "Of note, BRAT1 mutations are linked with neurodegenerative diseases and neurodevelopmental disorders such as rigidity and multifocal-seizure syndrome, although the exact molecular mechanisms underlying disease pathology are not well understood." (PMID 39833546, 2025). "Interestingly, BRAT1 variants are associated with diverse clinical conditions, from neonatal seizures to neurodevelopmental disorders, but it ́s potential role in brain tumors is largely unknown." (PMID 39833546, 2025).
tumor (4 papers, 2014 to 2025). "Our data reveals that the pro-migratory, pro-invasive phenotype of BRAT1-proficient tumors can be effectively curtailed by CurD, with significantly reduced numbers of brain-penetrating GSCs in the tumor microenvironment following treatment." (PMID 39833546, 2025). "Treatment with CurD, particularly in combination with radiation, effectively reduces tumor migration and brain tissue infiltration, suggesting BRAT1 targeting as a promising therapeutic strategy for GBM." (PMID 39833546, 2025). "Further, an analysis of the more recent CGGA database revealed that BRAT1 expression increases with tumor grade." (PMID 39833546, 2025). "The present study assessed functions and putative druggability of BRCA1-associated ATM activator 1 (BRAT1) as a crucial factor driving key aspects of GBM, including enhanced DNA damage response and tumor migration." (PMID 39833546, 2025). "Our 3D approach revealed a reduction in tumor cell spreading and frequency distribution, again indicating a decreased migration potential and invasiveness by blocking BRAT1 using CurD." (PMID 39833546, 2025). "One case of HGIN was found to have 2 tumor-associated genes with germline mutations, including NQO1 and BRAT1." (PMID 39792765, 2025). "After confirming suppressed BRAT1 expression, we found reduced BRAT1 expression in multiple cell lines induces growth retardation, increased apoptosis, and reduced tumor growth in vivo." (PMID 25070371, 2014). "Together, these results indicate that BRAT1 is involved in tumor cell growth, tumorigenesis and cell motility." (PMID 25070371, 2014). "Tumor size of BRAT1 knockdown cells was almost half of control HeLa cells throughout the time course, indicating that BRAT1 regulates tumor cell growth." (PMID 25070371, 2014). "In addition, we used an orthotopic GBM mouse model to confirm the essential role of BRAT1 in promoting tumor survival." (PMID 39833546, 2025). "Therefore, BRAT1-depletion significantly enhanced median overall survival from 42.5 days (d) of shCtrl NCH644 tumor-bearing mice to 55 d, indicating that BRAT1 depletion prolonged survival." (PMID 39833546, 2025). "In combination with the data obtained from the numerous functional assays employed in this study [wound healing assay (IBIDI), 3D transwell migration assay, in vivo orthotopic mice model and OTC ex vivo tumor growth], these findings collectively support the pro-migratory function of BRAT1 in GBM." (PMID 39833546, 2025). "Importantly, treatment with CurD enhanced the limiting effect of IR on tumor growth, indicating that combination of conventional therapy with BRAT1 inhibition may be an interesting therapeutic strategy." (PMID 39833546, 2025). "We demonstrate that BRAT1 depletion sensitizes GBM cells to radiation and inhibits tumor growth and invasion in both in vitro and in vivo models." (PMID 39833546, 2025). "In line with the observed suppressing effect of BRAT1 on its expression, Cav-1 has been described to function as a putative tumor suppressor in GBM, further highlighting the notion of targeting BRAT1 to inhibit the migrative and invasive capacity of this tumor." (PMID 39833546, 2025). "Biochemical analysis indicated that pathogenic forms of the BRCT domain of BRCA1 protein (e.g. M1775R) do not bind to BRAT1, suggesting BRCA1/BRAT1 interaction is important for BRCA1’s tumor-suppressive functions." (PMID 25070371, 2014).
neurological disease (2 papers, 2022 to 2026). "However, the molecular role of BRAT1 and the mechanism/s by which mutations in this gene trigger a variety of neurological disorders remain unknown." (PMID 36028512, 2022). "Importantly, impairments in Integrator function are also evident in patient-derived cells from BRAT1 related neurological disease." (PMID 36028512, 2022).
autosomal recessive disease (1 paper, 2021). Autosomal recessive form of disease. "RMFSL is a recently discovered autosomal recessive disease caused by the BRAT1 gene mutations." (PMID 33816000, 2021).
BRAT1 also shares sentences with these, for which no sentence is quoted: neurodegenerative disease (3 papers); breast carcinoma (2); Intellectual disability (2); atherosclerosis (1); cervical carcinoma (1); Cognitive impairment (1); esophageal squamous cell carcinoma (1); gastric cancer (1); glioblastoma (1); Hypertonia (1); infection (1); liver cancer (1); lymphoma (1); neurodevelopmental disorder with cerebellar atrophy and with or without seizures (1); Obesity (1); ocular motor apraxia (1); Ohtahara syndrome (1); ovarian carcinoma (1); Respiratory insufficiency (1); Rigidity and (1); Seizure (1).